TMPRSS2 (transmembrane serine protease 2)
Diseases named in the same sentence as TMPRSS2 in open-access papers (continued):
Sharing a sentence is not in itself a finding about the gene and the disease.
prostate carcinoma (continued). "In prostate cancer, one specific fusion (TMPRSS2-ERG) is the most common genetic alteration, being found in over 50% of patients." (PMID 27105842, 2016). "Among the commonly used prostate cancer cell lines, VCaP is the only cell line that harbors TMPRSS2/ERG translocation and expresses ERG protein." (PMID 27191272, 2016). "The use of EVs was also examined as a potential platform to non-invasively differentiate Bx Pos versus Bx Neg patients via the detection of known prostate cancer genes TMPRSS2:ERG, BIRC5, ERG, PCA3 and TMPRSS2." (PMID 27144529, 2016). "Since these two types of genetic alterations, i.e., SPOP mutations and TMPRSS2-ERG fusions, similarly lead to ERG stabilization, it is conceivable that their incidences are mutually exclusive in prostate cancers." (PMID 27200299, 2016). "Another common genomic aberration in prostate cancer is at TMPRSS2 locus where frequent rearrangements create various fusion genes." (PMID 27127882, 2016). "For example, bioinformatics approaches led to the discovery of the TMPRSS2-ETS gene fusion in prostate cancer and the EML4-ALK fusion in non-small-cell lung cancer." (PMID 27105842, 2016). "It has been shown that ERG increases expression of neurotransmitter reporters and TMPRSS2-ERG fusion blocks neuroendocrine cell differentiation to allow prostate cancer proliferation." (PMID 27626693, 2016). "A previous mass spectrometry analysis of ERG immunoprecipitated from prostate cancer cells with a TMPRSS2/ERG fusion, identified S215 phosphorylation, indicating that this modification can occur in vivo." (PMID 25885538, 2015). "Our results point out a concrete clinical application for prostate cancer therapy based on TMPRSS2-ERG knockdown." (PMID 25933120, 2015). "The TMPRSS2-ERG gene fusion has previously been reported as a clinical indicator for prostate cancer formation." (PMID 26575822, 2015). "In VCaP cells, a human prostate cancer cell line overexpressing both AR and the TMPRSS2-ERG gene fusion, an androgen response element (ARE)-targeted Py-Im polyamide significantly downregulates AR driven gene expression." (PMID 26571387, 2015). "Earlier studies have provided evidence for distinct molecular subgroups of prostate cancers defined by TMPRSS2:ERG fusions and several genomic deletions." (PMID 26230842, 2015). "Earlier studies had provided evidence for distinct molecular subgroups of prostate cancers defined by TMPRSS2:ERG fusions and several genomic deletions." (PMID 25894226, 2015). "Genetic alterations involving TMPRSS2-ERG alterations and deletion of key tumor suppressor genes are associated with development and progression of prostate cancer (PCa)." (PMID 25906751, 2015). "The AR and its fusion-gene target TMPRSS2-ERG are important regulators of oncogenic pathways in prostate cancer cells." (PMID 26035357, 2015). "Positive HOOK3 immunostaining was linked to TMPRSS2:ERG rearrangement and ERG positivity in prostate cancers." (PMID 26230842, 2015). "Several studies already demonstrated the importance of knocking down ERG over-expression by siRNA in prostate cancer; one of them has suggested the targeting of TMPRSS2-ERG fusion with siRNA delivered via liposomal nanovectors." (PMID 25933120, 2015). "TMPRSS2 was up-regulated and this is in agreement with reports of it being more highly expressed in prostate carcinoma compared to normal prostate epithelium." (PMID 26683658, 2015). "The VCaP human prostate cancer cell line expresses wild type AR and contains the TMPRSS2-ERG fusion." (PMID 26571387, 2015). "The fact that only approximately half of prostate cancer cases are TMPRSS2-ERG positive contributed to the even smaller number of TMPRSS2-ERG positive cases in our study." (PMID 26294063, 2015). "Common genetic alteration in prostate cancer, TMPRSS2-ERG fusion, is believed to be an early event in prostate carcinogenesis." (PMID 26337081, 2015).
prostate carcinoma (continued). "For example, the most studied fusion in prostate cancer is formed between the TMPRSS2 and ERG genes, resulting in ERG transcription being driven by the androgen-responsive TMPRSS2 promoter." (PMID 26626734, 2015). "Alterations in the expression of prostate cancer marker candidate genes TMPRSS2-ERG (transmembrane protease, serine 2; ETV-related gene) and PCA3 (prostate cancer antigen 3) have previously been detected by us and others." (PMID 26294063, 2015). "Knowing that a significant percentage of prostate malignancy harbours the TMPRSS2-ERG junction oncogene, our aim is to introduce a new potential therapeutic approach by siRNA targeting TMPRSS2-ERG junction oncogene in patients with prostate cancer." (PMID 25933120, 2015). "Expression of CRISP3 is prostate-specific, and CRISP3 is up-regulated in a subset of prostate cancers, especially prostate cancer with the TMPRSS2-ERG fusion gene." (PMID 26485759, 2015). "More recently, PRISM-SRM assays have been utilized for accurately measuring 16 distinct peptides from various domains of TMPRSS2-ERG gene fusion products in prostate cancer cell lines and patient-derived tumor tissues." (PMID 25889691, 2015). "ETS family gene fusions, primarily including ERG (and less frequently, ETV1, ETV4, ETV5 or FLI1), are found in approximately 50 % of prostate cancers, the most common fusion being TMPRSS2-ERG." (PMID 26684754, 2015). "More than half of all prostate cancers, particularly those of young patients, carry gene fusions linking the androgen-regulated TMPRSS2 gene with the transcription factor ERG." (PMID 26230842, 2015). "About 50% of prostate cancers are characterized by the TMPRSS2:ERG fusion, which results in overexpression of the ERG transcription factor and massive transcriptional changes." (PMID 26030748, 2015). "S215 phosphorylation has been observed by mass spectrometry of ERG immunoprecipitated from VCAP prostate cancer cells, indicating that this residue is phosphorylated in cells with the TMPRSS2:ERG fusion." (PMID 25885538, 2015). "PCA3 and TMPRSS2-ERG are commonly overexpressed biomarkers in prostate cancer, but reports have emerged demonstrating altered expression also in areas outside the tumour foci in cancerous prostates." (PMID 26294063, 2015). "A recent study focused on Usp9X in the context of a frequent prostate carcinoma-related genetic translocation (TMPRSS2-ERG) that facilitates tumor growth and thus not only represents a diagnostic aid, but also a potential therapeutic target." (PMID 26008975, 2015). "We studied the extent and location of the mRNA expression of two suggested prostate cancer markers, TMPRSS2-ERG fusion gene and PCA3, in a systematic way in cross-sections of cancerous prostates containing both histologically benign and carcinoma areas." (PMID 26294063, 2015). "In conclusion, this study offers a new prospect of treatment for prostate cancer based on siRNA-squalene nanoparticles targeting TMPRSS2-ERG junction oncogene." (PMID 25933120, 2015). "In conclusion, we used an experimental approach that mimics the prostate tumours in their physiological environment and points out a concrete clinical application for prostate cancer therapy based on TMPRSS2-ERG knockdown." (PMID 25933120, 2015). "Prostate cancer (PC) can be stratified into distinct molecular subtypes based on TMPRSS2-ERG gene fusion status, but its potential prognostic value remains controversial." (PMID 26478752, 2015). "In prostate cancer, the fusion gene TMPRSS2-ERG was found in 50% of patients, and it is used to classify patient groups." (PMID 24675677, 2014). "Due to the high incidence of TMPRSS2-ERG fusion in prostate cancer, recent studies have mainly focused on mapping ERG signaling networks in prostate." (PMID 24504051, 2014). "Transmembrane protease, serine 2 and v-ets erythroblastosis virus E26 homolog (TMPRSS2-ERG) gene fusions are the common molecular signature of prostate cancer." (PMID 24739220, 2014).
prostate carcinoma (continued). "Laboratory findings indicated that CRISP3 is a direct target of ERG and is strongly overexpressed in prostate cancers with the TMPRSS2-ERG fusion gene." (PMID 24739220, 2014). "These experiments suggest that TMPRSS2-ERG is related to factors known to indicate poor prognosis for of prostate cancer patients." (PMID 24505269, 2014). "It is important to understand the activation or repression of target genes and proteins in response to various stimuli and the assembly in signal transduction in TMPRSS2-ERG fusion-positive prostate cancer cells." (PMID 24739220, 2014). "The transmembrane protease, serine 2 v-etserythroblastosis virus E26 oncogene homolog (TMPRSS2-ERG) translocation presented in many prostate cancers." (PMID 27351008, 2014). "In prostate cancer ERG protooncogene frequently gains hormonal control by seizing gene regulatory elements of TMPRSS2 through genomic fusion events." (PMID 24418414, 2014). "It is encouraging to note an increased interest in inducing apoptosis in fusion-positive prostate cancer cells and disulfiram/sunitinib cotreatment induced apoptosis in TMPRSS2-ERG fusion-positive VCaP prostate cancer cells." (PMID 24739220, 2014). "Based on a historical watchful waiting cohort, an association between TMPRSS2-ERG, evaluated as positive immune staining, and shorter survival of prostate cancer patients was identified." (PMID 24505269, 2014). "Although tremendous advances have been made in unraveling various facets of TMPRSS2-ERG-positive prostate cancer, many research findings must be sequentially collected and re-interpreted." (PMID 24739220, 2014). "The relevance of the TMPRSS2 rearrangements to the pathogenesis, prognosis, and targeted therapy of prostate cancer has made it a predictive biomarker for prostate cancer." (PMID 24499728, 2014). "Experimental evaluation of the predicted composite element suggested that this element confers NKX3.1-mediated repression to the TMPRSS2-ERG fusion gene in prostate cancer cells." (PMID 24418414, 2014). "The usefulness of TMPRSS2-ERG as a prognostic marker for prostate cancer has been heavily studied with different results." (PMID 24505269, 2014). "Expressing prostate cancer cells pretreated with celastrol was reported to dose-dependently inhibit TMPRSS2-ERG fusion, AR and AR3 gene expression." (PMID 24739220, 2014). "In general, various signaling pathways are dysregulated in TMPRSS2-ERG fusion-positive prostate cancer cells." (PMID 24739220, 2014). "About 90% of gene fusions in prostate cancer are accounted by the fusion between the transmembrane protease, serine 2 (TMPRSS2), that is a strong androgen-regulated gene and the ERG gene, a v-ets erythroblastosis virus E26 oncogene homolog (avian)." (PMID 26317031, 2014). "Most of the studies concerning TMPRSS1 and TMPRSS2 are done with prostate cancer, and very little is known about their role in breast cancer." (PMID 25029565, 2014). "Rearrangements between the androgen regulated TMPRSS2 gene promoter and the ETS-related ERG gene result in TMPRSS2-ERG fusion transcripts that have been found in approximately half of prostate cancer cases in the Western world." (PMID 24418414, 2014). "Numerous studies have evaluated the association of TMPRSS2-ERG and outcome of prostate cancer patients with varying results." (PMID 24505269, 2014). "The fusion between ERG coding sequences and the TMPRSS2 promoter is the most prevalent in prostate cancer (CaP)." (PMID 25221645, 2014). "This is similar to what was found in prostate cancer in which the genomic breakpoints of TMPRSS2-ERG fusion gene was shown to differ among 29 patient samples, with none of them occurring at the same location." (PMID 24675677, 2014). "Fusion of the androgen-dependent TMPRSS2 gene to ETS-transcription factor ERG (TMPRSS2:ERG) is one of the most common genetic alterations in prostate cancer occurring in 50%–70% of tumors." (PMID 25243131, 2014).
prostate carcinoma (continued). "Gene fusion between the ERG proto-oncogene and TMPRSS2 promoter is a major genomic alteration observed in approximately 50% of prostate cancers." (PMID 24616882, 2014). "Many groups have analyzed the presence of TMPRSS2:ERG fusion or ERG protein expression in prostate cancer cohorts with variable outcome." (PMID 25243131, 2014). "Approximately half of the prostate cancer cases harbor the TMPRSS2-ERG gene fusions in Western countries." (PMID 24418414, 2014). "ERG target genes such as calcium channel, voltage-dependent, L type, α-1D subunit (CACNA1D) were significantly upregulated in TMPRSS2-ERG positive prostate cancer cells." (PMID 24739220, 2014). "ERG immunohistochemistry is an easy to perform methodology for detecting TMPRSS2:ERG fusion in prostate cancer." (PMID 25243131, 2014). "Transient transfection of TMPRSS2-ERG in prostate cancer cells stimulated endogenous OPN expression." (PMID 24739220, 2014). "To evaluate NKX3.1 in TMPRSS2-ERG fusion harboring prostate cancer cells we utilized the siRNA depletion strategy." (PMID 24418414, 2014). "We are among the first to use a panel of TMPRSS2:ERG subtype markers for urine-based prostate cancer detection with high specificity and sensitivity." (PMID 24133629, 2013). "In our studies, prostate cancer specific genes such as TMPRSS2 and AR have been enriched in leukemia ChIPs, although transcriptional regulation by ERG was not detectable at the mRNA level (data not shown)." (PMID 23300998, 2013). "Accordingly, demethylation of the TDRD1 promoter in TMPRSS2:ERG-negative prostate cancer cells by DNA methyltransferase inhibitors resulted in TDRD1 induction." (PMID 23555854, 2013). "Recent studies indicate that gene fusion of TMPRSS2-ERG promotes prostate cancer when PTEN is concurrently lost." (PMID 23466879, 2013). "Analogous to TMPRSS2/ERG in prostate cancer, the SLC1A2 fusion in gastric cancer is thought to be driven by strong expression of its 5′ partner, CD44." (PMID 23637631, 2013). "It is possible that TMPRSS2-fusion positive prostate cancer patients would uniquely responsive to androgen deprivation therapy, as this would limit the amount of androgen-induced oncogene being expressed." (PMID 24349831, 2013). "ERG is the most commonly fused member of the ETS family, with a TMPRSS2:ETS fusion occurring in approximately 46% of prostate cancers, in a study of needle biopsies in patients with prostatic malignancy." (PMID 24018887, 2013). "ERG, a member of the ETS transcription factor family, is frequently overexpressed in prostate cancer as a result of its fusion to the androgen-responsive Tmprss2 gene." (PMID 23472063, 2013). "In conclusion, we propose a urine-based clinical test for early detection of clinically significant prostate cancer using a panel of multiple TMPRSS2:ETS fusion markers." (PMID 24133629, 2013). "We observed again a number of copy number changes, many of those characteristic of prostate cancer, such as the TMPRSS2-ERG deletion." (PMID 23561577, 2013). "Data of the entire panel across different individuals showed that prostate cancer patients with PTEN deletion also tended to exhibit abnormal results in TMPRSS2/ERG FISH." (PMID 24098661, 2013). "We tested a set of cell lines positive for the BCR-ABL1 fusion and prostate cancers positive for the TMPRSS2-ERG fusion." (PMID 23341502, 2013). "The identification of recurrent translocations between the androgen-responsive Tmprss2 gene and members of the Ets family of transcription factors in prostate cancer (PCa) has changed the panorama of PCa biology." (PMID 23472063, 2013). "The regulation of TMPRSS2 by AR has been shown directly in a limited number of AR+ luminal prostate cancer cell lines and indirectly in primary prostate cancers where TMPRSS2 expression correlates with expression of other AR-regulated genes." (PMID 22860005, 2012).
prostate carcinoma (continued). "In this study, we utilized a chemical biology drug sensitivity screen to explore disulfiram mechanistic details and to identify compounds potentiating the effect of disulfiram in TMPRSS2-ERG fusion positive prostate cancer cells." (PMID 23251544, 2012). "In this study, we utilized a chemical biology compound sensitizing screen to study aldehyde dehydrogenase (ALDH) inhibitor disulfiram mechanism of action and to identify potential synergistic agents for disulfiram in TMPRSS2-ERG positive prostate cancer cells." (PMID 23251544, 2012). "Clinical studies have suggested that the TMPRSS2-ERG translocation occurs early in prostate cancer development." (PMID 22860005, 2012). "The TMPRSS2:ERG chromosomal rearrangement identified by Chinnayan’s pioneering studies in 2005 has become a molecular event of historic proportions in the prostate cancer field." (PMID 22641253, 2012). "A similar pattern was observed in prostate cancer: the complete exon-1 of TMPRSS2 was identified to fuse with ETV1 or ERG as one of the most recurrent rearrangements." (PMID 22496636, 2012). "A comprehensive understanding of TMPRSS2 transcriptional regulation is important in considering the effect of androgen deprivation therapy upon prostate cancers harboring TMPRSS2-ERG fusions." (PMID 22860005, 2012). "Approximately 50% of prostate cancer samples from PSA screened cohorts contain a TMPRSS2-ERG fusion gene." (PMID 22860005, 2012). "We consider a profiling experiment on a publicly available prostate cancer dataset: the task is to select a list of predictive biomarkers and a classifier to predictively discriminate prostate cancer patients carrying the TMPRSS2-ER gene fusion." (PMID 22615778, 2012). "The TMPRSS2 promoter has been investigated in various prostate cancer cell lines, where it has been shown to be highly expressed in luminal cells and positively regulated by androgen receptor." (PMID 22860005, 2012). "The ERG gene is frequently translocated to the TMPRSS2 promoter region; the resulting TMPRSS2-ERG fusion protein is positively expressed in half of human prostate cancer cases." (PMID 22454635, 2012). "Taken together, these clinical data support the occurrence of TMPRSS2-ERG translocation as an early event in prostate cancer that is subsequently selected during malignant transformation." (PMID 22860005, 2012). "Cancer outlier profile analysis (COPA) was developed to identify transcripts up-regulated in only a small subset of cancer samples, and has successfully been used to identify recurrent TMPRSS2 gene fusions in prostate cancer." (PMID 23216803, 2012). "These aggressive prostate cancers fuse the promoter of TMPRSS2, an androgen responsive gene, to an ETS family transcription factor, such as ETV1 or ERG, both of which have also been identified in joining to EWS in ESFT to form an oncogenic fusion protein." (PMID 22383402, 2012). "VCaP is a model for TMPRSS2-ERG positive prostate cancer, expressing wild type AR, whereas LNCaPs harbour a mutant AR (T877A) with extended ligand specificity." (PMID 22761906, 2012). "TMPRSS2-ERG gene fusions have been reported in approximately 50% of over 1500 clinically localized prostate cancer samples." (PMID 22811706, 2012). "Tissue sections from wild type and transgenic fusion mice were stained with Ab2805, as this antibody has been validated in histological analysis of human TMPRSS2-ERG prostate cancers." (PMID 22860005, 2012). "One of the prostate cancer-specific chromosome translocation is the fusion of TMPRSS2 and ERG genes, which has been reported in 60–70% of prostate cancer tissues." (PMID 23272087, 2012). "In this work, the transcriptomes of a series of prostate carcinomas, stratified by the TMPRSS2-ERG fusion gene status, were analyzed using whole-genome expression microarrays." (PMID 21814574, 2011). "TMPRSS2-ERG gene fusions occur in about 50% of all prostate cancer cases and represent promising markers for molecular subtyping." (PMID 22142399, 2011).